IGF2BP3 (insulin like growth factor 2 mRNA binding protein 3)
Diseases named in the same sentence as IGF2BP3 in open-access papers (continued):
Sharing a sentence is not in itself a finding about the gene and the disease.
colon cancer (continued). "It has been confirmed that upregulation of IGF2BP3 promotes initiation and progression of multiple cancers, such as bladder cancer and colon cancer." (PMID 34312475, 2021). "Meanwhile, the expression of IGF2BP3 in our colon cancer specimens was also investigated by IHC and Western Blotting." (PMID 32993738, 2020). "All these results indicated IGF2BP3 repressed S phase as well as the proliferation of colon cancer by reading m6A modification of CCND1." (PMID 32993738, 2020). "Our research comprehensively investigated m6A modification in colon cancer and subsequently focused on the m6A modification read by IGF2BP3." (PMID 32993738, 2020). "String these results together, knockdown of IGF2BP3 promoted cell cycle arrest, thus repressed the DNA replication and proliferation in colon cancer." (PMID 32993738, 2020). "In summary, we demonstrated m6A reader IGF2BP3 regulated cell cycle and angiogenesis of colon cancer via reading m6A modification of CCND1 and VEGF respectively." (PMID 32993738, 2020). "Both GO and KEGG showed DNA replication to be most possible IGF2BP3 regulatory mechanism in colon cancer." (PMID 32993738, 2020). "We also demonstrated IGF2BP3 worked as a prognosis marker as well as a potential therapeutic target for colon cancer." (PMID 32993738, 2020). "As expected, IGF2BP3 was significantly overexpressed in colon cancer tissues compared with normal bowel tissues." (PMID 32993738, 2020). "Further assays of HUVECs based on colon cancer cell-derived CM also confirmed knockdown of IGF2BP3 repressed angiogenesis in colon cancer." (PMID 32993738, 2020). "To investigate IGF2BP3 regulated mechanism in colon cancer, we extracted the most relevant genes related to IGF2BP3 in TCGA databases for GO and KEGG analysis." (PMID 32993738, 2020). "Among them, IGF2BP3 was demonstrated as a predictor of progression as well as poor survival in colon cancer." (PMID 32993738, 2020). "Moreover, the GEPIA database analysis indicated that patients with colon cancer who exhibited high levels of IGF2BP3 expression were correlated with an unfavorable prognosis." (PMID 40530014, 2025). "Ultimately, we identified that IGF2BP3 may regulate ferroptosis in colon cancer cells through its interaction with SLC7A11." (PMID 40530014, 2025). "Overall, our findings hold substantial clinical applications and suggest that IGF2BP3 could be a promising candidate for therapeutic intervention to improve treatment efficacy in colon cancer." (PMID 40530014, 2025). "Notably, the elucidation of IGF2BP3’s regulatory role in ferroptosis provides new insights into potential therapeutic strategies for colon cancer." (PMID 40530014, 2025). "In the future, combination therapies involving traditional chemotherapy drugs and small molecule compounds could be used for drug-resistant colon cancer patients or to enhance therapeutic efficacy, especially in those with high IGF2BP3 expression." (PMID 40530014, 2025). "Literature research indicated that miR-98-5p might act as an upstream regulator, targeting IGF2BP3 and participating in the ferroptosis process in colon cancer cells." (PMID 40530014, 2025). "Down-regulation of IGF2BP3 in colon cancer can inhibit DNA replication and angiogenesis." (PMID 39028290, 2024). "Additionally, growing data suggested that IGF2BP3 was a useful biomarker for several malignancies, including colon cancer and GC." (PMID 38725047, 2024). "Furthermore, IGF2BP3 has been identified as a promising biomarker for various cancers including colon cancer." (PMID 37658049, 2023). "While VEGF is an important growth factor for tumor angiogenesis, knockdown of IGF2BP3 may inhibit angiogenesis in colon cancer by regulating the reduction of VEGF expression." (PMID 38053093, 2023). "In colon cancer, IGF2BP3 expression promotes angiogenesis by targeting m6A-methylated VEGF mRNA." (PMID 37280679, 2023). "Therefore, thorough identification of IGF2BP3 targets in colon cancers is important for understanding its function." (PMID 37582618, 2023).
colon cancer (continued). "Our study identified IGF2BP3 as a regulator of ICD in colon cancer for the first time." (PMID 36497433, 2022). "For the first time, we identified IGF2BP3 as a potential ICD regulator in colon cancer." (PMID 36497433, 2022). "This indicated that IGF2BP3 functioned as an inducer in the ICD process of colon cancer." (PMID 36497433, 2022). "In recent years, some studies have increasingly recorded the effects of IGF2BP3 on basic processes in cancer biology, and its overexpression has been extensively related to adverse patient results in various tumors, such as colon cancer and gastric carcinogenesis." (PMID 35401168, 2022). "However, it is necessary to further verify the mechanisms and functions of IGF2BP3 in colon cancer by in vivo and in vitro experiments." (PMID 35677634, 2022). "IGF2BP3 might also be a reference to monitor the treatment of colon cancer and explore molecular mechanisms related to the progression of colon cancer." (PMID 35677634, 2022). "And the function of gene IGF2BP3 in immunotherapy was identified, which may contribute to more effective treatment in patients with colon cancer." (PMID 35677634, 2022). "IGF2BP3 has been characterized as an oncoprotein and a useful biomarker for a variety of cancers, including adenocarcinoma, intrahepatic cholangiocarcinoma, squamous esophageal cancer, and colon cancer." (PMID 35615150, 2022). "Additionally, they indicated that IGF2BP3 repressed the S phase as well as the proliferation of colon cancer by reading m6A modification of CCND1." (PMID 34721530, 2021). "Knockdown of IGF2BP3 repressed angiogenesis in colon cancer via regulating VEGF." (PMID 32993738, 2020). "IGF2BP3 was a possible prognosis marker and potential therapeutic target of colon cancer." (PMID 32993738, 2020). "After its initial identification, IGF2BP3 was found to be a mainly overexpressed member of its protein family in various tumor types, such as squamous cell carcinoma, lung cancer, melanoma, colon cancer and liver cancer." (PMID 32648571, 2020). "In conclusion, we revealed the m6A read role of IGF2BP3 in colon cancer." (PMID 32993738, 2020). "Interestingly, knockdown of IGF2BP3 successfully increased the percentage of S phase in whole cell cycle, inhibited DNA replication and proliferation of colon cancer cells." (PMID 32993738, 2020). "Knockdown of IGF2BP3 also repressed MVD of colon cancer in vivo." (PMID 32993738, 2020). "In summary, knockdown of IGF2BP3 in colon cancer cells repressed angiogenesis by regulating VEGF." (PMID 32993738, 2020). "Overexpression of IGF2BP3 also promoted the invasion of colon cancer in both vivo and vitro." (PMID 32993738, 2020). "Furthermore, accumulating evidences demonstrated that IGF2BP3 represented a promising biomarker in different cancers, such as colon cancer and GC." (PMID 28399871, 2017). "After its initial identification, IGF2BP3 has soon been explicated to be a mainly over-expressed member among the family in various tumor types, such as squamous cell carcinoma, lung cancer, melanoma, colon cancer, liver cancer." (PMID 28399871, 2017). "In addition, the m6A reader IGF2BP3 regulates cell cycle and angiogenesis in colon cancer." (PMID 38053093, 2023). "IGF2BP3 may be used as a prognostic indicator of colon cancer." (PMID 34858499, 2021). "Finally, we confirmed the knockdown of IGF2BP3 repressed the growth of colon cancer in vivo." (PMID 32993738, 2020). "IGF2BP3 was a newly reported m6A reader, whereas its role in colon cancer remains unclear." (PMID 32993738, 2020). "Additionally, IGF2BP3 in colon cancer with advanced stage also showed further overexpressed." (PMID 32993738, 2020). "Targeting the miR-98-5p/IGF2BP3/SLC7A11 axis offers a promising therapeutic strategy to enhance ferroptosis sensitivity and improve colon cancer outcomes." (PMID 40530014, 2025). "IGF2BP3 drives ferroptosis resistance in colon cancer by stabilizing SLC7A11 mRNA, while miR-98-5p antagonizes this pathway via IGF2BP3 downregulation." (PMID 40530014, 2025).
colon cancer (continued). "It is IGF2BP3 that targets cyclin D1 and VEGF to regulate the cell cycle and angiogenesis of colon cancer." (PMID 38355626, 2024). "Overexpression of ABCB1 inducing multidrug resistance (MDR) desensitizes colon cancer cells to chemotherapy drugs with ABCB1 substrate specificity, resulting from enhanced stability of ABCB1 transcript via IGF2BP3 reading its m6A region." (PMID 37280679, 2023). "IGF2BP3 binds to and reads the m6A recognition site in VEGF mRNA in colon cancer cells, thus regulating the expression and stability of VEGF mRNA." (PMID 38053093, 2023). "We found increased accumulation of IGF2BP3 mRNA and protein expression in COAD and human colon cancer tissues." (PMID 35677634, 2022). "Additional, one previous study demonstrated m6A “readers”, IGF2BP3, participates VM formation by sustaining VEGF expression and cell proliferation in colon cancer." (PMID 35595748, 2022). "However, the m6A reader role of IGF2BP3 in colon cancer remains unclear." (PMID 32993738, 2020). "In colon cancer, USP11 could bind IGF2BP3 and block its ubiquitination degradation, which then promotes tumor proliferation and metastasis." (PMID 38565547, 2024). "And some studies have shown that the knockout of IGF2BP3 can inhibit DNA replication and angiogenesis in the S phase of the cell cycle by reading the m6A modification of CCND1 and vascular endothelial growth factor (VEGF) respectively in colon cancer." (PMID 36793593, 2023). "IGF2BP3 expression is elevated in COAD and colon cancer tissues." (PMID 35677634, 2022). "Some studies have indicated that IGF2BP3 can be used as a prognostic signature in colon cancer but its mechanism has not been systematically analyzed." (PMID 35677634, 2022).
colorectal cancer (43 papers, 2011 to 2025). A primary or metastatic malignant neoplasm that affects the colon or rectum. "The diagnostic efficacy of IGF2BP3 was evaluated through ROC curves, which revealed that IGF2BP3 displayed the highest diagnostic accuracy for esophageal cancer and the lowest for colorectal cancer." (PMID 40765570, 2025). "The cohort-dependent associations between overall survival and both Polr2d and Igf2bp3 have been observed in colorectal cancer and glioblastoma, respectively." (PMID 21649900, 2011). "Also, significant associations were found in colorectal cancer between IGF2BP3 positivity, poorer differentiation, and increased mortality, thus serving as a promising diagnostic biomarker for colorectal cancer in which higher expression indicates poorer prognosis." (PMID 36761737, 2023). "Studies have shown that in colorectal cancer, IGF2BP3 modulates the expression of T cell chemokines such as CCL5 and CXCL9/10, thereby influencing T cell recruitment to the tumor site." (PMID 41589308, 2025). "KEGG analysis indicated that IGF2BP3 participates in modulating the reactive oxygen species (ROS) signaling pathway in colorectal cancer." (PMID 40530014, 2025). "RBM15 has been shown to enhance the stability and expression of KLF1 mRNA in colorectal cancer through IGF2BP3-mediated m6A modification." (PMID 39716068, 2024). "The expression of IGF2BP3 in tissue specimens was found to be a biomarker for the diagnosis of colorectal cancer in endoscopic biopsies." (PMID 36983731, 2023). "There were also reports that the overexpression of IGF2BP3 was closely related to poor prognosis in endometrial carcinoma, oral squamous cell carcinoma, colorectal cancer, ovarian cancer, and lung adenocarcinoma." (PMID 37655157, 2023). "Previous studies have reported that IGF2BP3 plays oncogenic roles by activating PI3K/AKT pathway in colorectal cancer, Ewing sarcoma, and glioblastoma." (PMID 37663284, 2023). "The relationship between IGF2BP3 expression and chemotherapy resistance has received much attention in recent years, for example in ovarian cancer and colorectal cancer." (PMID 36732736, 2023). "BBR has been reported to induce G0/G1 phase arrest in colorectal cancer cells by downregulating the targeted gene IGF2BP3." (PMID 36937842, 2023). "We examined the expression of has_circ_0074854, miR-2110, ENO2, and IGF2BP3 in 30 colorectal cancer tissues and investigated their interrelationships." (PMID 37644235, 2023). "In this work, we identified the mRNA targets of IGF2BP3 in the colorectal carcinoma cell line HCT116 using our optimized IR-PAR-CLIP method." (PMID 37582618, 2023). "The optimized IR-PAR-CLIP protocol revealed novel RNA targets of IGF2BP3 in a human colorectal carcinoma cell line." (PMID 37582618, 2023). "In colorectal carcinoma, IGF2BP3 has been shown to activate the MEK1/ERK signaling pathway and promote anti-apoptotic pathways through the stabilization of Bcl-2 and Bcl-xL transcripts." (PMID 37760460, 2023). "Here, we optimized the PAR-CLIP protocol to study RNA targets of endogenous IGF2BP3 in a human colorectal carcinoma cell line." (PMID 37582618, 2023). "High expression of IGF2BP3 can promote the invasiveness of colorectal cancer cells in vitro and in vivo." (PMID 33796449, 2021). "IGF2BP3 is highly expressed in human cancers, including lung cancer, melanoma, colorectal cancer, liver cancer, and squamous cell carcinoma of the head and neck." (PMID 35127504, 2021). "IGF2BP3 has been reported to promote carcinogenesis in colorectal cancer, ovarian cancer and pancreatic ductal adenocarcinoma." (PMID 33177247, 2020). "IGF2BP3 has been reported to serve as an independent prognostic marker in a variety of cancers including ovarian carcinoma, astrocytoma, colorectal cancer, oral carcinoma, endometrial carcinoma and pancreatic ductal adenocarcinoma." (PMID 29212181, 2017). "In conclusion, this study is the first to perform RT-PCR for IGF2BP3 on a sizable population of colorectal cancer patients." (PMID 26244168, 2015).
colorectal cancer (continued). "The present study is the first to utilize RT-PCR to quantitatively assess IGF2BP3 mRNA expression in a reasonable sized population of colorectal cancers." (PMID 26244168, 2015). "Several studies addressing IGF2BP3 expression in colorectal cancer have detected significantly elevated IGF2BP3 expression in the majority of aggressive colorectal carcinomas (CRCs), suggesting that IGF2BP3 expression correlates with an unfavorable prognosis." (PMID 26327240, 2015). "In colorectal cancer, IGF2BP1 and IGF2BP3 might act as potential biomarkers for screening high-risk groups and cancer patients." (PMID 37280679, 2023). "In addition, IGF2BP3 has been demonstrated to enhance the tumor growth and metastatic spread of colorectal cancer cells." (PMID 36686749, 2022). "Moreover, IGF2BP3 overexpression has been observed in colorectal cancer and the knockdown of IGF2BP3 has been shown to repress angiogenesis and DNA replication through reading m6A modification of VEGF and CCND1, respectively." (PMID 35047491, 2021). "The expression of IGF2BP3 has a significant influence on biological functions related to tumorigenesis, such as cell proliferation and migration in various human cancers, including esophageal cancer, breast cancer, colorectal cancer, and prostate cancer." (PMID 35127504, 2021). "Moreover, increased IGF2BP3 expression facilitates the aggression of colorectal cancer cells via regulating epithelial‐mesenchymal transition." (PMID 33094561, 2020). "Likewise, IGF2BP3 is involved in constructing prognostic models of colorectal cancer." (PMID 37298373, 2023). "However, the exact molecular mechanisms of IGF2BP3 in colorectal cancer (CRC) oncogenesis, progression, and drug resistance remain unclear." (PMID 37658049, 2023). "In colorectal cancer, IGF2BP2 and IGF2BP3 can stimulate vasculogenic mimicry formation by separately stabilizing the transcripts of EphA2 and VEGF via interaction with their m6A sites." (PMID 37280679, 2023). "Moreover, the IGF2BP3/ELAV-like RNA binding protein 1 (ELAVL1) complex is involved in the stabilization of oncogenic transcripts, thus promoting tumorigenicity of colorectal cancer." (PMID 35677634, 2022). "IGF2BP3, as an important RBP, has been reported to interact with ELAVL1 to recognize cell cycle and cell proliferation related genes, and lead to prolonged half-life of mRNA molecules and increased expression of target genes, thereby promoting colorectal cancer cell proliferation." (PMID 40083693, 2025). "Previous research has confirmed that glycyrrhizin ameliorates colorectal cancer progression by regulating NHEJ pathway through inhibiting HMGB1‐induced DNA damage response and glycyrrhizin effectively reverses the cancer‐promoting effects of IGF2BP3 overexpression in bladder cancer." (PMID 39904827, 2025). "IGF2BP3 could directly interact with the m6A-modified region on ATP-binding cassette transporters subfamily B member 1 (ABCB1) mRNA, resulting in the high expression of ABCB1 and the elevation of ABCB1 mRNA stability in colorectal cancer cells." (PMID 34657141, 2021). "Moreover, it was reported that IGF2BP3 could facilitate tumor immune escape by down-regulating the stress-induced ligands MICB and ULPB2 in colorectal carcinoma." (PMID 34446007, 2021). "IGF2BP3 mRNA expression in colorectal cancers (CRC) has not been well studied." (PMID 26244168, 2015).